SMAD4 (SMAD family member 4)
Diseases named in the same sentence as SMAD4 in open-access papers (continued):
Sharing a sentence is not in itself a finding about the gene and the disease.
metastasis (4 papers, 2006 to 2023). The spread or migration of cancer cells from one part of the body (where they first appeared) to another. "Thereby, synchronous lung metastasis more frequently showed mutations in ATM, KIT, PIK3CA and SMAD4 (each with 3/5 cases as compared to 1/5 cases with metachronous liver metastases)." (PMID 27756406, 2016). "Our results showed that Begg’s funnel plots between SMAD4 and clinicopathological parameters (tumor differentiation, lymph node metastasis, TNM stage, age and sex) were symmetric, and the P values of Egger’s test were 0.600, 0.271, 0.587, 0.700, and 0.482, respectively." (PMID 37478236, 2023).
mucinous neoplasm (4 papers, 2017 to 2023). "In a more recent study, SMAD4 mutation was found more frequently in high-grade mucinous adenocarcinomas versus low-grade mucinous tumors." (PMID 28267766, 2017). "Their results indicate that loss of SMAD4 immunohistochemical expression is associated with loss of heterozygosity at chromosome 18q and is always associated with aggressive histologic features in disseminated appendiceal mucinous neoplasms." (PMID 37509254, 2023).
nasopharyngeal carcinoma (4 papers, 2019 to 2022). A carcinoma arising from the nasopharyngeal epithelium. "Additionally, miR-34a inhibits EMT in nasopharyngeal carcinoma by targeting Smad4 through the TGF-β/Smad pathway." (PMID 31349837, 2019).
overlap syndrome (4 papers, 2021 to 2026). "This case illustrates the early onset and clinical complexity of SMAD4-associated JPS-HHT overlap syndrome." (PMID 42110114, 2026).
rhabdomyosarcoma (4 papers, 2012 to 2024). A rare aggressive malignant mesenchymal neoplasm arising from skeletal muscle. "Studies have reported SMAD4 overexpression in Rhabdomyosarcoma cells and suggest that this upregulation is through TGFβ1." (PMID 24688641, 2012). "Resveratrol was evaluated against rhabdomyosarcoma soft tissue malignant tumour cells and was found to decrease cell growth, reduce cells in the S phase, arrest G0/G1 transition and reduce TGF‐β1and Smad4 expression at the protein and mRNA levels in PLA‐802 human alveolar rhabdomyosarcoma cell." (PMID 35384373, 2022).
triple-negative breast carcinoma (4 papers, 2018 to 2022). An invasive breast carcinoma which is negative for expression of estrogen receptor (ER), progesterone receptor (PR), and human epidermal growth factor receptor 2 (HER2). "Furthermore, RBMS3 has been reported to stabilise several members of the SMAD family such as SMAD2 in zebrafish and SMAD2, SMAD3 and SMAD4 in triple-negative breast cancer cells." (PMID 36421707, 2022). "Moreover, our results suggest that the interaction and desumoylation between SENP2 and Smad4 promote cell migration in triple-negative breast cancer cells." (PMID 29955155, 2018). "However, in triple-negative breast cancer, Smad4 inhibits micro-peptide synthesis of LINC00665." (PMID 35563845, 2022). "In triple-negative breast cancer, activated TGF-β/Smad4 signaling significantly increases the mRNA level of 4E-BP1, which inhibits the translation of the micro-peptide CIP2A-BP by binding it to eIF4F." (PMID 35563845, 2022).
autism (3 papers, 2021 to 2025). Persistent deficits in social interaction and communication and interaction as well as a markedly restricted repertoire of activity and interest as well as repetitive patterns of behavior. "TNRC6B, PTEN, AGO1, SKI, and SMAD4 were the most frequent targets, and miR-92a-3p had the most target autism risk genes." (PMID 34744804, 2021).
Barrett's oesophagus (3 papers, 2015 to 2023). "We wonder whether early EAC or severely dysplastic Barrett's oesophagus was present at non-trivial levels in some of our post-treatment specimens, for example reflecting the loss of the SMAD4 mutation after treatment in cancer #8." (PMID 27045317, 2016).
bile duct cancer (3 papers, 2012 to 2024). "Studies have found that LNC-LFAR1 expression inhibition can inhibit bile duct cancer cell proliferation, migration, and invasion, and reduce the expression of Vimentin, Tgf-β1, Smad2, and Smad4." (PMID 35456382, 2022).
chronic pancreatitis (3 papers, 2015 to 2025). A chronic inflammatory process causing damage and fibrosis of the pancreatic parenchyma. "The combination of TGFα overexpression and Smad4 deletion in the pancreas of the STP mice presented a number of histologic similarities to human chronic pancreatitis, including increased fibrosis and development of PanIN-1& -2 lesions." (PMID 25803032, 2015).
COVID-19 (3 papers, 2023 to 2024). A disease caused by infection with severe acute respiratory syndrome coronavirus 2. "Of the 107 patients with ascertained COVID-19, 50 had a known genetic mutation in ENG (18/50), ACVRL1 (31/50) or SMAD4 (1/50)." (PMID 37140873, 2023). "Thus, whether SMAD4 plays a specific role in inflammatory cardiomyopathy and cardiovascular disease during recovery from COVID-19 deserves further experimental research." (PMID 37457560, 2023). "In the COVID-19 comparison group, five DEPs, PPP1CA, YWHAH, YWHAB, YWHAZ, and TP53BP2, were enriched with the first three upregulated and TP53BP2 downregulated, whereas the PQ group exhibited enrichment only in Smad4 within this pathway." (PMID 39301288, 2024). "Additionally, Smad4 exhibited significant downregulation in the PQ group, yet this difference was not significant in the COVID-19 comparison group." (PMID 39301288, 2024).
endometriosis (3 papers, 2023 to 2024). The growth of functional endometrial tissue in anatomic sites outside the uterine body. "The ENCODE and ChEA Transcription Factor gene target analysis also identified SMAD4 as a major regulatory factor controlling transcription in endometriosis." (PMID 38402336, 2024). "On the other hand, regulation of genes by the NFE2 Like BZIP Transcription Factor 2 (NFE2L2) and SMAD4 transcription factors was highly enriched in the endometriosis dataset." (PMID 38402336, 2024). "We also calculated the overlapping numbers of endometriosis-associated DEGs (determined from Day 4 EPC, FC > 1.4, < 0.4, FDR < 0.05), SMAD4, and H3K27Ac bound genes." (PMID 38402336, 2024). "In our study, we investigated the expression of SMAD4 in the endometrium of women with endometriosis." (PMID 37047609, 2023). "A heterogeneous profile of the expression levels of the studied genes (BMP-7, SMAD4 and CDH1) and miR-52-3p in the ectopic endometrium with respect to its eutopic counterpart suggests the loss of endometrial epithelium phenotype in women with endometriosis." (PMID 37047609, 2023). "The different patterns of BMP7, SMAD4, and CDH1 gene expression in ECE, EUE, and the control endometrium observed by us suggests the loss of the endometrial epithelium phenotype in women with endometriosis and demonstrates their involvement in the pathogenesis and pathomechanism of this disease." (PMID 37047609, 2023). "This may also be the reason why relatively few statistically significant results have been obtained with respect to the associations between BMP7, SMAD4, CDH1, and miR-542-3p expression levels and the biochemical parameters and clinical features of endometriosis." (PMID 37047609, 2023). "Analysis of endometrial stromal cells from individuals with endometriosis identified NFE2L2 and SMAD4 as the top two transcription factors controlling gene expression during decidualization." (PMID 38402336, 2024). "A novelty of our work was the analysis of miR-542-3p, BMP7, SMAD4, and CDH1 expression in PBMCs obtained from women diagnosed with endometriosis compared to those obtained from healthy women." (PMID 37047609, 2023). "A positive correlation was demonstrated between the SMAD4 and CDH1 genes in biopsy material derived from the eutopic endometrium (Rho = 0.681538, p = 0.000176) and in PBMC patients with endometriosis (Rho = 0.526154, p = 0.006900)." (PMID 37047609, 2023). "The aim of this study was to evaluate the expression profile of miR-542-3p and the EMT markers (BMP7, SMAD4, CDH1) in matched eutopic endometrium (EUE) and ectopic endometrium (ECE) samples from women with endometriosis in relation to healthy women." (PMID 37047609, 2023). "Few studies have assessed the expression of SMAD4 and BMP7 in endometriosis." (PMID 37047609, 2023). "The analysis of the expression levels of BMP7, SMAD4, CDH1, and miR-542-3p according to the stage of endometriosis demonstrated a statistically significant increase in the level of BMP7 expression in the group of patients with stage III compared to stage IV endometriosis (p = 0.035602)." (PMID 37047609, 2023). "In patients with endometriosis, TGF-β1 and SMAD4 are upregulated, which may suggest the activation of the TGF-β/SMAD signaling pathway." (PMID 37047609, 2023). "The binding studies showed that there were notable changes in the distribution of both SMAD4 and H3K27ac between the endometrial stromal cells of individuals with and without endometriosis, suggesting that the gene expression changes were a result of altered transcription factor binding events." (PMID 38402336, 2024). "However, given that SMAD4 enrichment was decreased at the ID1 and ID3 promoter regions, and this corresponds with decreased ID gene expression, it was likely that BMP signaling pathways also impair SMAD1/5/4 binding activities in the stromal cells from individuals with endometriosis." (PMID 38402336, 2024).
endometriosis (continued). "BMP7, SMAD4, CDH1, and miR-542-3p expression levels were assessed in PBMCs from endometriosis patients and in PBMCs from patients without endometriosis, who constituted the control group (C2)." (PMID 37047609, 2023). "Additionally, since SMAD4 is a central and critical component of both TGF-β and BMP signaling, based on our observations, it can be hypothesized that if its expression is disturbed in endometriosis, the functionality of all proteins of this pathway may be changed." (PMID 37047609, 2023). "Although we did not investigate these mechanisms, the different patterns of SMAD4 expression shown for the ECE and EUE samples in comparison with the control samples indicates that endometrial cell function may be altered in women with endometriosis." (PMID 37047609, 2023).
Hepatitis (3 papers, 2017 to 2024). Inflammation of the liver. "Interestingly, HCC liver exhibited a significantly higher percentage of nuclear positive Smad4 compared with healthy, hepatitis and cirrhotic livers." (PMID 39346534, 2024). "Though the relationship between SMAD4 and miR-21 in PDAC has not been established, recent studies have shown that miR-21 inhibits the SMAD4 signaling pathway in hepatitis and rheumatoid arthritis." (PMID 38891080, 2024).
Infertility (3 papers, 2023 to 2025). "The authors of other studies also demonstrated reduced expression of the SMAD4 transcript but in the ovarian cumulus cells from women with peritoneal endometriosis-associated infertility compared with the control group, as well as in a rat model of intrauterine adhesion." (PMID 37047609, 2023). "Specifically, SMAD4 knockdown in mouse ovaries led to severe oocyte abnormalities and the premature luteinization of granulosa cells, as well as infertility." (PMID 39057967, 2024).
Intellectual disability (3 papers, 2021 to 2023). "Gene ontology analysis by IPA software revealed that transcriptional targets of AR, KDM5B, and SMAD4 that were differentially expressed in response to BPA treatment were significantly associated with “autism spectrum disorder or intellectual disability”." (PMID 36803626, 2023). "In addition to AR targets, KDM5B targets dysregulated in male and female pups, and SMAD4 targets dysregulated in male pups were also significantly associated with “autism spectrum disorder or intellectual disability”." (PMID 36803626, 2023).
iron deficiency (3 papers, 2020 to 2022). "It has been proven in both in vitro and in vivo conditions that Smad4, an iron-dependent transcription factor, can limit Hif-2α transcriptional activity and iron deficiency leads to proteasomal degradation of Smad4." (PMID 33396831, 2020).
laryngeal squamous cell carcinoma (3 papers, 2019 to 2020). A squamous cell carcinoma that arises from the larynx. "The highly homologous miRNA to hsa-mir-301b, hsa-miR-301a-3p, played a role in the emergence and development of laryngeal squamous cell carcinoma by directly regulating the Smad4." (PMID 30886579, 2019). "In addition to that, Yan and colleagues described an oncogenic role for hsa-miR-301a-3p in Laryngeal Squamous Cell Carcinoma development through inhibition of Smad4 and participation in the EMT process." (PMID 32498409, 2020). "Interestingly, miR301a-3p acts as an oncogene by targetting several tumor suppressor genes, including Smad4 in Laryngeal squamous cell carcinoma (LSCC)." (PMID 31940341, 2020).
liposarcoma (3 papers, 2016 to 2025). A usually painless malignant tumor that arises from adipose tissue. "Overall, over 15 ncRNAs were reported to play essential roles in modulating different cellular pathways, including apoptosis, WNT/β-catenin, TGF-β/SMAD4, EMT, interleukin, and YAP-associated pathways to influence liposarcoma development." (PMID 39736850, 2025). "In summary, we demonstrate that miR-193b controls cell growth and differentiation in liposarcoma by targeting multiple key components (PDGFRβ, SMAD4, and YAP1) in several oncogenic signaling pathways." (PMID 30824765, 2019). "Considering the potential interaction among PDGFRβ, SMAD4, and YAP1 in precipitating cancer development, inhibiting these targets by miR-193b can therefore help halt liposarcoma progression." (PMID 39736850, 2025). "Instead of affecting tumor growth, increased levels of SMAD4, as would result from the under-expression of miR-193b in DDLS, may contribute to liposarcoma progression and deregulation of differentiation in WDLS/DDLS." (PMID 30824765, 2019).
liver diseases (3 papers, 2018 to 2024). "Taken together, both the overexpression and presence of gene somatic mutations of SMAD4 in liver disease are bona fide indicators of a more aggressive disease." (PMID 30282914, 2018). "Moreover, the functional role of SMAD4 in the development of liver diseases has also been investigated by SMAD4 knockout mouse model in our previous work." (PMID 38385079, 2024).
mucinous adenocarcinoma (3 papers, 2017 to 2021). An invasive adenocarcinoma composed of malignant glandular cells which contain intracytoplasmic mucin.
myocardial infarction (3 papers, 2021 to 2024). Gross necrosis of the myocardium, as a result of interruption of the blood supply to the area, as in coronary thrombosis. "They found that miR-146b overexpression significantly decreased the myocardial infarct size and cardiomyocytes apoptotic rates and release of creatine kinase and lactate dehydrogenase during IRI by targeting Smad4 and modulating the expression of c-fos and c-JUN in the myocardium." (PMID 33996940, 2021).
Oral leukoplakia (3 papers, 2013 to 2022). A thickened white patch on the oral mucosa that cannot be rubbed off. "Although these data suggest the close relationship between SMAD4 loss‐related inflammation and carcinogenesis, little is known about the association between SMAD4 expression and inflammation in precancerous lesions such as leukoplakia of the oral cavity." (PMID 28256094, 2017). "One study reported that low SMAD4 expression in oral leukoplakia is associated with increased malignant transformation and lymphocyte infiltration, suggesting that the combination of low SMAD4 expression and high lymphocyte infiltration may predict the risk of malignant transformation." (PMID 35326482, 2022). "The combination of SMAD4 expression and histological grade of dysplasia was a better predictor for the malignant transformation of oral leukoplakia." (PMID 23826135, 2013). "We found that the combination of strong SMAD4 expression and high grade of dysplasia predicted the malignant transformation of oral leukoplakia better than either single factor did." (PMID 23826135, 2013). "The combination of strong SMAD4 expression and high grade of dysplasia was a better predictor for the malignant transformation of oral leukoplakia than either single factor." (PMID 23826135, 2013).
schizophrenia (3 papers, 2013 to 2025). A major psychotic disorder characterized by abnormalities in the perception or expression of reality. "This defect was rescued by inhibiting bone morphogenetic protein (BMP) signaling through the knock-down of mothers against decapentaplegic homolog 4 (SMAD4), further implicating dysregulated astrocytic development in the pathophysiology of schizophrenia." (PMID 40427508, 2025). "Another Smad family member - Smad4 has been proven to be related to SCZ, since forebrain-specific Smad4 knock-out mice shows typical endophenotype of schizophrenia." (PMID 23369358, 2013).
skin tumor (3 papers, 2011 to 2023). "Significantly, Smad4−/− tumors exhibited inactivation of PTEN and activation of AKT, and codeletion of the Smad4 and PTEN resulted in accelerated hair loss and skin tumor formation." (PMID 23326666, 2012). "Smad4/PTEN double knockout mice had accelerated skin tumor formation in comparison with MMTV-Cre or K5-Cre driven Smad4 deletion mice." (PMID 22204491, 2011).
small cell lung carcinoma (3 papers, 2015 to 2024). Small cell lung cancer (SCLC) is a highly aggressive malignant neoplasm, accounting for 10-15% of lung cancer cases, characterized byrapid growth, and early metastasis. "Further, patients with never/ever smoking history who present with small-cell lung cancer have a different mutation profile compared with smokers, including a high frequency of EGFR, MET, and SMAD4 mutations." (PMID 31058075, 2019).
thyroid tumor (3 papers, 2011 to 2025). A benign or malignant neoplasm affecting the thyroid gland. "This reveals the potential role of the TGF-β-SMA4 signaling pathway in the malignancy-associated modulation of TIME and stimulates further discovery of the diagnostic and prognostic role of STAT6 and SMAD4 in thyroid tumors." (PMID 39936166, 2025). "Similarly, the promoter of SMAD4 was isolated and cloned from patients with thyroid tumor, demonstrating the importance of GC box on the activity of SMAD4." (PMID 33925909, 2021). "Our results demonstrate that STAT6 and SMAD4 molecules are interconnected with the number of certain classes of immune cells, and therefore may play a role in the regulation of the immune microenvironment of thyroid tumors." (PMID 39936166, 2025).
acute promyelocytic leukemia (2 papers, 2012 to 2013). An aggressive form of acute myeloid leukemia (AML), characterized by arrest of leukocyte differentiation at the promyelocyte stage, due to a specific chromosomal translocation t(15;17) in myeloid cells. "A direct role of miR-130a in inhibition of Smad4 synthesis has been demonstrated in neutrophil precursors and the repression of Smad4 mRNA by miR-146a has likewise been demonstrated in the acute promyelocytic leukemia cell line NB4." (PMID 23554893, 2013).